TRIR (telomerase RNA component interacting RNase)
Description:
Exoribonuclease that is part of the telomerase RNA 3' end processing complex and which has the ability to cleave all four unpaired RNA nucleotides from the 5' end or 3' end with higher efficiency for purine bases.
Synonyms: C19orf43; MGC2803; fSAP18; TERCIR
Tractability: PROTAC: ubiquitination databases record sites on it.
Gene: Protein-coding gene on chromosome 19 (12,730,640 to 12,734,684, reverse strand). Ensembl gene ENSG00000123144.
Subcellular location (Human Protein Atlas): Nucleoplasm
Gene Ontology:
Molecular function: 3'-5' exonuclease activity; 5'-3' exonuclease activity; protein binding
Biological process: rRNA catabolic process
Genetic constraint (gnomAD): Loss-of-function variants: 5 observed, 12.01 expected, observed/expected ratio (o/e) 0.42, 90% interval 0.22 to 0.88. The synonymous counts are far from expectation, so gnomAD's model fits this gene poorly and the ratio says little. Missense variants: 206 observed, 208.77 expected, observed/expected ratio (o/e) 0.99, 90% interval 0.88 to 1.11. Synonymous variants: 134 observed, 98.94 expected, observed/expected ratio (o/e) 1.35, 90% interval 1.18 to 1.56.
Homologues: Orthologues: chimpanzee TRIR (100% identical), macaque TRIR (99% identical), dog TRIR (96% identical), pig TRIR (96% identical), rabbit TRIR (95% identical), guinea pig TRIR (95% identical), mouse Trir (92% identical), rat Trir (91% identical), tropical clawed frog trir (47% identical), zebrafish trir (43% identical).
Diseases named in the same sentence as TRIR in open-access papers:
TRIR is named in the same sentence as 5 diseases in open-access papers, as found by Europe PMC text mining. Sharing a sentence is not in itself a finding about the gene and the disease. The quoted sentences say what the papers report.
breast carcinoma (1 paper, 2022). "There have been few reports addressing the role of TRIR in breast cancer." (PMID 36553667, 2022).
melanoma (1 paper, 2022). A malignant, usually aggressive tumor composed of atypical, neoplastic melanocytes. "However, in melanoma, TRIR inhibits angiogenesis and is related to the activity of cancer cells." (PMID 36553667, 2022).
cancer (2 papers, 2022). A tumor composed of atypical neoplastic, often pleomorphic cells that invade other tissues. "TRIR is an exoribonuclease that may have functions in RNA cleavage, cancer suppression, and antiviral activities like other ribonucleases, although it remains to be a novel target in tumors with largely unknown functions." (PMID 36003795, 2022).
tumor (2 papers, 2021 to 2024). "For example, we observed that the HOOK2 gene in case 19 was highly expressed in the tumor sample (19T), but not in its matched normal (19N) and stroma (19S) samples, while those genes around HOOK2 (SNORD41, TRIR, and JUNB) had similar levels of expression in all three samples." (PMID 33916417, 2021).
TRIR also shares sentences with these, for which no sentence is quoted: acute megakaryoblastic leukemia (1 paper).